SYP (synaptophysin)
Diseases named in the same sentence as SYP in open-access papers (continued):
Sharing a sentence is not in itself a finding about the gene and the disease.
Cerebral ischemia (9 papers, 2014 to 2024). Restriction of arterial blood supply to the brain associated with insufficient oxygenation to support the metabolic requirements of the tissue. "To examine the detrimental effect of ischemic damage on synaptic proteins following cerebral ischemia, we studied the expression of synaptophysin, and synaptosomal-associated protein-25 (SNAP-25)." (PMID 31798514, 2019). "These outcomes are in line with previous reports of enlarged granular TH terminals and large synaptophysin-positive dots after cerebral ischemia/reperfusion in the rat CPu." (PMID 31920641, 2019). "We semi-quantified the SNAP-25, GAP-43 and synaptophysin immunofluorescence since these indicators of synaptic structure have previously been used to evaluate neuroplasticity in other models of cerebral ischemia." (PMID 25259609, 2014). "The protein expression of PSD-95 as well as SYP decreased after modeling, and there was a significant difference in the protein expression of SYP (P < 0.05), suggesting that there were different degrees of structural damage and reduction after cerebral ischemia." (PMID 39749196, 2024).
Ewing sarcoma (9 papers, 2021 to 2026). A small round cell tumor that lacks morphologic, immunohistochemical, and electron microscopic evidence of neuroectodermal differentiation. "Immunohistochemistry was positive for vimentin, NKX2.2, CD99, and synaptophysin, confirming the diagnosis of Ewing sarcoma." (PMID 42281714, 2026). "Adamantinoma-like Ewing sarcoma (ALES) is a rare variant of ES defined by complex epithelial differentiation, with an expression of pancytokeratin, CD99, p40, and synaptophysin and frequent keratin pearl formation." (PMID 35059992, 2022). "Ewing sarcoma can be misdiagnosed as DSRCT due to positive staining for keratin and/or synaptophysin." (PMID 39777304, 2024).
adrenocortical carcinoma (8 papers, 2010 to 2024). "Immunohistochemically benign and malignant adrenocortical carcinoma are positive for synaptophysin, inhibin, Melan-A, and calretinin." (PMID 25685588, 2015). "Adrenocortical carcinomas are usually positive for synaptophysin and strongly positive for vimentin." (PMID 22400493, 2012). "Moreover, demethylation treatment of the adrenocortical carcinoma cell line H295R using 5-aza resulted in increased expression of SYP, which also supports the finding that SYP expression is regulated by an epigenetic mechanism." (PMID 31352437, 2019). "Renshaw and Granter conducted a study and reported that inhibin and synaptophysin positivity could be used in definitive diagnosis of adrenocortical carcinoma." (PMID 27975081, 2016). "In this study, we showed that sarcomatous component of the tumor also focally retains positivity for Melan-A, synaptophysin and calretinin, supporting the notion that sarcomatous area of the tumor has indeed originated from the adrenocortical carcinoma rather than representing a collision tumor." (PMID 20687934, 2010).
amyloid (8 papers, 2010 to 2025). "The AppNL‐G‐F mice begin to develop typical β‐amyloid plaques starting after 4 months of age, demonstrating synaptic alterations, as indicated by reductions in synaptophysin and PSD95 immunoreactivities." (PMID 40356480, 2025). "Using immunofluorescence confocal microscopy, we likewise demonstrated that BACE1 immunoreactivity overlapped that of synaptophysin within many of the neuritic dystrophies adjacent to amyloid plaques." (PMID 23820808, 2013). "MW-151 treatment prevented loss of synapses, as measured by western blots for the levels of PSD-95, synaptophysin, syntaxin, and synaptosomal-associated protein 25 (SNAP25), without affecting amyloid plaque load or soluble Aβ concentrations." (PMID 35783099, 2022). "Similar to the 5XFAD brain, BACE1 and synaptophysin displayed significant co-localization surrounding amyloid plaques, while MAP2 did not overlap with BACE1 in the AD brain." (PMID 23820808, 2013). "Our preliminary studies also confirmed the early‐stage presence of β‐amyloid plaques in AppNL‐G‐F mice, with no quantitative changes detected for CHT1 and synaptophysin in tissue extracts." (PMID 40356480, 2025).
glomus tumor (8 papers, 2012 to 2025). A rare benign or malignant mesenchymal neoplasm arising from cells that resemble the modified smooth muscle cells of the glomus body. "A literature review revealed that glomus tumors in visceral organs positive for synaptophysin show histological atypical features in most cases." (PMID 26187280, 2015). "More importantly, most of the reported glomus tumors positive for synaptophysin have atypical histological features." (PMID 26187280, 2015). "These previous reports and the present case suggest that synaptophysin positivity may correlate with atypical histological features in glomus tumors arising in visceral organs." (PMID 26187280, 2015). "This unique case and literature review yielded interesting findings and enabled us to postulate that synaptophysin positivity may be indicative of atypical histological features in glomus tumors arising in visceral organs." (PMID 26187280, 2015). "Moreover, other studies have reported cases of glomus tumors with atypical histological features and synaptophysin positivity in the kidney, esophagus and bronchus." (PMID 26187280, 2015). "Probably due to their extreme rarity, our series includes no cases of gastrointestinal glomus tumors, which were frequently found to express synaptophysin but not chromograninA." (PMID 34350470, 2021). "In general, glomus tumors in peripheral soft tissues are synaptophysin-negative, but reports of glomus tumors focally positive for synaptophysin have been documented." (PMID 26187280, 2015). "Although there is one report of a case of glomus tumor without atypia that stained positive for synaptophysin, most cases of glomus tumors positive for synaptophysin exhibit either histological atypia or clinically malignant behavior, such as metastasis." (PMID 26187280, 2015). "Interestingly, glomus tumors positive for synaptophysin occur not in peripheral soft tissues, but in visceral organs." (PMID 26187280, 2015). "Glomus tumors and GVM arising from soft tissue typically do not express synaptophysin, in contrast to glomus tumor originating in visceral organs such as the stomach, liver, esophagus, duodenum, and kidney." (PMID 40918549, 2025).
ischemia (8 papers, 2009 to 2025). A hypoperfusion of the BLOOD through an organ or tissue caused by a PATHOLOGIC CONSTRICTION or obstruction of its BLOOD VESSELS, or an absence of BLOOD CIRCULATION. "In the Tat peptide- and Control-SH3GL2-treated groups, PSD95 protein levels gradually decreased 1 day and 4 days after ischemia, while synaptophysin and SNAP-25 levels increased 4 days after ischemia." (PMID 33572372, 2021). "Disturbed sleep 3 days after focal cerebral ischemia is shown to reduce axonal sprouting, expression of synaptophysin, and the ischemia-stimulated neural and vascular cell proliferation in rats." (PMID 24478645, 2013). "DAPT significantly stimulated higher gene expression of synaptophysin in the CMS-treated ischemia animals (P<0.05)." (PMID 22912748, 2012). "Furthermore, there was a decrease in synaptophysin protein expression in the MCAO+CMS animals compared to the ischemia rats (P<0.05)." (PMID 22912748, 2012). "Since neuroplastic changes have been shown to be a delayed phenomenon, GAP-43 and synaptophysin expression were investigated by western blotting experiments in the two concentric samples of cortical tissue P1 and P2 at longer time points of ischemia (8, 15 and 30 d)." (PMID 19956568, 2009). "Concerning GAP-43 expression, 3-AB treatment induces a reduced expression already significant at 8 d and at one month post-ischemia whereas statistical differences were found for synaptophysin expression at longer time points (15 and 30 d of ischemia) between the two groups of animals." (PMID 19956568, 2009). "SYP expression was significantly increased in all complications associated with brain damage and nervous system dysfunction: IVH (0.61, −0.73; p ≤ 0.001), ischemia (0.77, −0.7; p ≤ 0.03), asphyxia (0.91, −0.71; p ≤ 0.003), CNS depression syndrome (0.45, −0.72; p ≤ 0.005)." (PMID 40003962, 2025). "Recent evidences have shown that LCN DBS increased the expression of perilesional synaptophysin, a crucial marker for long-term potentiation, in parallel with functional recovery, indicating a potential improvement in synaptic plasticity and post-ischemia motor recovery attributable to DBS." (PMID 39697542, 2024). "PSD95, synaptophysin, and SNAP-25 levels were assessed in the hippocampus by Western blot analysis because ischemia and Tat-SH3GL2 have been shown to affect synaptic plasticity in the hippocampus." (PMID 33572372, 2021). "Transient forebrain ischemia reduced PSD95, synaptophysin, and SNAP-25 levels in the hippocampus 1 day and 4 days after ischemia." (PMID 33572372, 2021). "In the Tat-SH3GL2-treated group, however, PSD95, synaptophysin, and SNAP-25 levels were significantly higher in the hippocampus at 1 day and 4 days after ischemia compared to those in the Tat peptide or Control-SH3GL2-treated groups." (PMID 33572372, 2021). "It is known that ischemia induces severe progressive inner retinal degeneration and down-regulation of synaptic proteins, such as PSD95 and synaptophysin." (PMID 25954153, 2015).
prostate adenocarcinoma (8 papers, 2019 to 2024). "A widely used pan‐neuronal marker notwithstanding, TUBB3 expression was not related to neuroendocrine differentiation (NED, defined as positivity of generic NE markers chromogranin A and synaptophysin) in conventional prostate adenocarcinoma (p = 0.653)." (PMID 34318630, 2021). "According to an immunohistochemical analysis, he tested negative for PSA, NKX3.1, and p501s, the common markers of prostatic adenocarcinoma, but was tested positive for synaptophysin and chromogranin A." (PMID 31631483, 2019). "Finally, analysis of 42 LuCaP patient-derived xenografts and primary adenocarcinoma samples shows a positive correlation between αVβ3, but not αVβ6, and the neuronal marker synaptophysin; it also demonstrates that αVβ3 is absent in prostatic adenocarcinomas." (PMID 33481853, 2021). "In prostate adenocarcinoma cells, we observed that short-term REST knock-down led to an increase of BAF53B (ACTL6B) mRNA and protein levels, but the effect was modest, while other neuronal genes known to be negatively controlled by REST (e.g., synaptophysin) were highly upregulated." (PMID 33144576, 2020). "The tumor presenting the highest NTR1 expression was a poorly differentiated prostatic adenocarcinoma (CK20−, CK7−, PSAp+, p63−, p504s+) without neuroendocrine differentiation (CgA-, synaptophysin-), Gleason 9, node-positive, T3, R0." (PMID 30959962, 2019).
sarcoma (8 papers, 2007 to 2025). A usually aggressive malignant neoplasm of the soft tissue or bone. "The combination of GFAP, Olig-2, synaptophysin, WT-1 and reticulin staining can help differentiate sarcoma and neuroepithelial tumors." (PMID 38926750, 2024). "Evaluation of our synaptophysin results with those reported in the literature in sarcomas/mesenchymal neoplasms showed that synaptophysin is most frequently expressed in CCS, DSRCT, ES, and neoplasms deficient for SMARCB1 and SMARCA4." (PMID 34350470, 2021). "Histopathology revealed characteristic GCTs with positive immunostaining for neural marker (S-100) and negative immunostaining for epithelial (cytokeratin, Cam 5.2, AE/A13), neuroendocrine (neuron specific enolase, chromogranin A, and synaptophysin) and sarcoma (desmin, vimentin) markers." (PMID 17355632, 2007). "In good accordance with these findings, the primary tumor in the patient localized in his left nasal cavity, showed positivity for both neuroendocrine (synaptophysin, CD56) and sarcoma markers (CD99), and had a high proliferation index." (PMID 40134582, 2025). "Besides neural cell adhesion molecules (CD56), other neuroendocrine markers synaptophysin (Syn), neuron-specific enolase (NSE), and chromogranin A (CgA) are often used in differential diagnosis of sarcoma." (PMID 35372059, 2022).
adrenocortical tumors (7 papers, 2010 to 2021). "Previous study revealed Synaptophysin (SYP) is ubiquitously expressed in adrenocortical tumors, but its function in CPA still need to be discovered." (PMID 31352437, 2019). "Recently, increasing evidence has clarified that SYP is ubiquitously expressed in adrenocortical tumours." (PMID 31352437, 2019). "Previous studies reported that SYP is ubiquitously expressed in adrenocortical tumours and its expression in adrenocortical adenomas may be associated with functions such as transport or secretion of glucocorticoids." (PMID 31352437, 2019). "This list can be further expanded by the adrenocortical neoplasms and pancreatic SPNs, which are other examples of NEN mimickers characterized by chromograninA negativity in the presence of synaptophysin." (PMID 34350470, 2021). "This can be distinguished from an adrenocortical tumor by positivity for other melanocytic makers such as S-100, HMB-45, tyrosinase and negativity of calretinin, synaptophysin and inhibin." (PMID 20687934, 2010). "Both adrenocortical tumors and pheochromocytomas stain positive for synaptophysin but adrenocortical tumors are negative for chromogranin." (PMID 32266384, 2020). "Concerning the specificity of STX1, many endocrine tumors known to express either CHGA or SYP, such as parathyroid and adrenocortical neoplasms, were consistently negative for STX1." (PMID 32059362, 2020). "Although the role of SYP in adrenocortical tumours has been previously reported, the mechanisms involved in abnormal expression of SYP in adrenocortical tumours had not yet clarified." (PMID 31352437, 2019). "Nevertheless, there was no study about the the mechanisms involved in SYP aberrantly expressed in adrenocortical tumours." (PMID 31352437, 2019).
medullary thyroid carcinoma (7 papers, 2012 to 2024). "Tumor markers used in medullary carcinoma include calcitonin, chromogranin, and synaptophysin." (PMID 35154933, 2022). "This tumor showed positivity for cytokeratin AE1/AE3, carcinoembryonic antigen, synaptophysin, chromogranin, TTF-1, S-100, and calcitonin, indicating medullary thyroid carcinoma with a Ki-67 proliferation index of 10%." (PMID 39553134, 2024). "Medullary thyroid carcinoma cells may be spindle-shaped; however, immunohistochemically, they are reactive for keratins, thyroid transcription factor-1 (thyroglobulin-negative), neuron-specific enolase, chromogranin (A, B and C), synaptophysin, opioid peptides and calcitonin." (PMID 24944660, 2014). "Calcitonin-negative medullary carcinoma of the thyroid can be encountered; synaptophysin and chromogranin are used to supplement the diagnosis." (PMID 35154933, 2022). "Non-staining with synaptophysin and chromogranin helped us in the differential diagnosis of medullary carcinoma of the thyroid and parathyroid neoplasms." (PMID 24884725, 2014). "Neoplastic cells showed strong immunoreactivity to chromogranin A and synaptophysin, but the immunohistochemical profile was inconsistent with medullary thyroid carcinoma in that the tumor was negative for calcitonin, carcinoembryonic antigen (CEA), and thyroid transcription factor-1 (TTF-1)." (PMID 22369355, 2012). "The tumors were consistent with a neuroendocrine phenotype; showing strong immunoreactivity to chromogranin A and synaptophysin, but the immunohistochemical profile was inconsistent with medullary thyroid carcinoma in that the tumor was negative for calcitonin, CEA and TTF-1." (PMID 22369355, 2012).
Merkel cell carcinoma (7 papers, 2004 to 2025). "All tumors included in the present study exhibited the classic morphology of Merkel cell carcinoma and expressed diffusely chromogranin A, synaptophysin, and cytokeratin 20 (dot-like expression pattern)." (PMID 36298750, 2022). "Merkel cell carcinomas also label for neuron specific enolase (virtually all), chromogranin B (100%), chromogranin A (72%), secretoneurin (22%), and synaptophysin (39%)." (PMID 15550173, 2004). "The nuclei of the carcinoma had a smudged, salt-and-pepper appearance; however, CK20, INSM-1, and synaptophysin were negative, excluding Merkel cell carcinoma." (PMID 41019495, 2025). "The possibility that the neoplasm was a Merkel cell carcinoma was considered; however, this was excluded by the lack of immunoreactivity against CK20, NSE and synaptophysin." (PMID 36548831, 2022). "However, CK20, synaptophysin, and INSM-1 are all negative, excluding Merkel cell carcinoma." (PMID 41019495, 2025).
renal cell carcinoma (7 papers, 2010 to 2024). "The purpose of the study was to examine serotonin, CD56, neurone-specific enolase (NSE), chromogranin A and synaptophysin by immunohistochemistry in renal cell carcinomas (RCCs) with special emphasis on patient outcome." (PMID 20462442, 2010). "Immunohistochemical staining was positive for the cytokeratins, AE1 and AE3, and negative for CD56, chromogranin A, synaptophysin, renal cell carcinoma marker, and CD10." (PMID 27549181, 2016). "In contrast, thyroid transcription factor 1 (TTF-1), anti-renal cell carcinoma (RCC), CD10, CK20, as well as synaptophysin, chromogranin A, thyroglobulin and transthyretin are negative." (PMID 35546652, 2022). "In contrast to renal cell carcinomas, most extra-adrenal paragangliomas are negative or only weakly or focally positive for keratins and are diffusely positive for neuroendocrine markers (synaptophysin, chromogranin, and CD56)." (PMID 24883221, 2014). "Positivity for neuroendocrine markers, such as synaptophysin, chromogranin, and CD56, and the absence of CD10 positivity differentiate LCNECs from high-grade renal cell carcinomas." (PMID 38933067, 2024).
rhabdomyosarcoma (7 papers, 2011 to 2025). A rare aggressive malignant mesenchymal neoplasm arising from skeletal muscle. "Immunohistochemistry showed positivity for rhabdomyosarcoma markers such as Desmin, MyoD1, and Myogenin in the rhabdomyosarcomatous component and positivity for neuroectodermal markers, including synaptophysin and chromogranin A in the neuroectodermal component." (PMID 41465905, 2025). "The present case is a unique cervical cancer, consisting of neuroepithelial components positive for CD99 and synaptophysin, immature / atypical intestinal glands positive for SALL4 and CDX-2, cartilage cells, and rhabdomyosarcoma, resembling sinonasal TCS." (PMID 31684979, 2019). "We also did not observe any alveolar rhabdomyosarcoma, which may express synaptophysin and chromograninA." (PMID 34350470, 2021).
tauopathy (7 papers, 2016 to 2025). Neurodegenerative disorders involving deposition of abnormal tau protein isoforms (tau proteins) in neurons and glial cells in the brain. "The reduced expression of synaptophysin and PSD95 in TG samples suggests synapse weakening and/or loss is an early feature of tauopathy, with postsynaptic structures exhibiting greater vulnerability." (PMID 38712321, 2024). "Additionally, metformin has been found to disrupt synaptic structure by reducing synaptophysin expression in tauopathy models." (PMID 41146261, 2025). "Increased Aβ levels, tauopathy, and neuroinflammation are reported as causative agents of synaptic dysfunction, and postsynaptic marker PSD95 and presynaptic marker synaptophysin are both reported to be downregulated in the presence of aggregated amyloid proteins." (PMID 36443837, 2022). "This is in agreement with a recent study showing that in mammalian models of tauopathy there is little evidence that synaptophysin expression is lost when normalized to NSE expression in brain regions affected by significant neurodegeneration (Bondulichet al., 2016)." (PMID 27524794, 2016).